SPRR5 (small proline rich protein 5)
Description:
Positively regulates keratinocyte differentiation by inducing genes associated with epidermal differentiation.
Gene: Protein-coding gene on chromosome 1 (152,947,206 to 152,949,255, forward strand). Ensembl gene ENSG00000283227.
Gene Ontology:
Biological process: positive regulation of keratinocyte differentiation